MIR627 (microRNA 627)
Synonyms: hsa-mir-627; MIRN627; mir-627
Gene: MicroRNA gene on chromosome 15 (42,199,570 to 42,199,666, reverse strand). Ensembl gene ENSG00000207712.
Homologues: Orthologues: chimpanzee ptr-mir-627 (100% identical).
Diseases named in the same sentence as MIR627 in open-access papers:
MIR627 is named in the same sentence as 1 disease in open-access papers, as found by Europe PMC text mining. Sharing a sentence is not in itself a finding about the gene and the disease.
MIR627 shares sentences with these, for which no sentence is quoted: lung disease (1 paper).